VDR (vitamin D receptor)
Diseases named in the same sentence as VDR in open-access papers (continued):
Sharing a sentence is not in itself a finding about the gene and the disease.
Hypertension (continued). "In conclusion, VDR and MEGALIN gene variations can affect prevalent MetS and the incidence rate of hypertension, respectively, among African-American urban adults." (PMID 29795187, 2018). "In mice lacking the vitamin D receptor (VDR‐null), the expression of resin and plasma angiotensin II were markedly elevated, resulting in the development of hypertension and cardiac hypertrophy." (PMID 40836860, 2025). "Mice with VDR deletion develop myocardial hypertrophy regardless of hypertension, excess RAS activation, or hypocalcemia." (PMID 34070202, 2021). "Mice experimentally lacking the VDR gene developed arterial hypertension independent of classical regulatory mechanisms such as plasma volume and osmolality." (PMID 34574039, 2021). "A multiple linear regression analysis with htTKV as dependent variable, including hypertension, CRP, eGFR, age, time since diagnosis, VDR, and 25(OH)D adjusted for season of the year showed that only the first three parameters were independent predictors of the former." (PMID 31179282, 2019). "These concepts could be critical in understanding the complex interplay between VDR and RAAS for hypertension and related inflammatory disorders." (PMID 27009470, 2016). "Mice lacking vitamin D receptor had an increased renin expression and angiotensin II production and developed also hypertension and cardiac hypertrophy." (PMID 26000280, 2015). "Mice lacking the VDR exhibit hypertension and cardiac hypertrophy due to increased renin expression and plasma angiotensin II production." (PMID 23349943, 2013). "Mice lacking the vitamin D receptor or α-hydroxylase (required for vitamin D activation), constitutively over-express renin and develop hypertension." (PMID 22759247, 2012). "However, the results of the multivariate regression analysis with htTKV as the dependent variable, including hypertension, CRP, eGFR, age, time since diagnosis, VDR and 25(OH)D adjusted for season of the year showed that only the first three parameters were independent predictors of the former." (PMID 31179282, 2019). "Therefore, the absence of vitamin D receptor activation leads to tonic upregulation of the renin-angiotensin system, eventually leading to hypertension and left ventricular hypertrophy and increasing the likelihood of MetS." (PMID 32153897, 2018). "It is the first time that the negative relationship of LRAT and VDR with childhood hypertension was found, suggesting that supplement of VA and VD in children with hypertension may play important roles in cardiovascular protection." (PMID 30631592, 2018). "Therefore, the absence of vitamin D receptor activation leads to tonic upregulation of the renin-angiotensin system, eventually leading to hypertension and left ventricular hypertrophy." (PMID 24586986, 2014). "Recent research conducted with mice without the Vdrgene (which codes for the vitamin D receptor) and the Cyp27B1 gene (which codes for alpha-1-hydroxylase) demonstrated thatthese animals had high levels of renin and, consequently, of angiotensin II,provoking hypertension and cardiac hypertrophy." (PMID 34178073, 2020). "Mice lacking vitamin D receptor (VDR) have elevated production of renin and angiotensin II, leading to hypertension, cardiac hypertrophy, and increased water intake." (PMID 20049157, 2010).
Insulin resistance (87 papers, 2010 to 2025). Increased resistance towards insulin, that is, diminished effectiveness of insulin in reducing blood glucose levels. "Several studies have found the influence of VDR polymorphisms on insulin resistance in the background of PCOS." (PMID 39866289, 2025). "More importantly, VDR has been shown to influence adipogenesis in adipose tissue, and the activation of VDR in adipose tissue is associated with insulin resistance and the expression of lipolysis-related genes." (PMID 41163042, 2025). "The association of vitamin D receptor gene polymorphisms with insulin resistance and type 2 diabetes has been investigated in many studies, but the results are inconsistent across different populations." (PMID 38233797, 2024). "Researchers also discovered that the VDR (vitamin D receptor) regulates vitamin D levels and calcium metabolism in the body, which are associated with endocrine dysfunction and insulin resistance." (PMID 38233797, 2024). "This study demonstrated that those with the BB genotype of VDR BsmI polymorphism were at higher risk for insulin resistance and developing type 2 DM." (PMID 38233797, 2024). "Adolescents with the BB genotype of VDR BsmI were observed to be associated with an increased risk of insulin resistance compared with the bb/Bb genotype." (PMID 38233797, 2024). "This study investigated the association between VDR SNPs and cardiometabolic phenotypic data in self-reported Hispanics (n = 1610) from the Arizona Insulin Resistance registry and Sangre Por Salud Biobank." (PMID 37432296, 2023). "In particular, the VDR gene polymorphisms BsmI (rs1544410) and FokI (rs2228570) were suggested to influence insulin secretion and insulin resistance." (PMID 37175993, 2023). "The VDR gene is implicated in the insulin metabolic pathway, and its polymorphism is linked to insulin resistance and secretion." (PMID 37836571, 2023). "The results of some studies suggest a relationship between VDR polymorphisms and insulin resistance, but this particularly associates the Bsm-I polymorphism with type 2 diabetes." (PMID 37375641, 2023). "The VDR is significantly expressed in pancreatic β-cells, and studies have linked SNPs in the VDR gene to insulin resistance and insulin secretory capacity." (PMID 37836571, 2023). "Deletion of VDR in mouse macrophages was associated with the induction of insulin resistance, as it led to accumulation of M2 macrophages in the liver, increased cytokine secretion, and hepatic glucose production." (PMID 37175993, 2023). "The present study showed a significant association between insulin resistance and VDR 1544410 G > A (BsmI) polymorphism among patients with T2DM who had poor glycemic control." (PMID 33567588, 2021). "This is supported by the expression of VDR on pancreatic β-cells and the association between VDR gene polymorphisms and insulin resistance." (PMID 31252555, 2019). "VDR signaling in macrophages regulates their phenotype and loss of myeloid VDR promotes insulin resistance and cardiovascular disease." (PMID 30828578, 2018). "Eighteen studies (4851 cases and 6174 controls) from 17 papers examining the association between the VDR FokIrs2228570 (C > T) variant and Insulin resistance related diseases susceptibility were included." (PMID 28822353, 2017). "Twenty-two studies (4294 cases and 4157 controls) in 17 papers examining the association between the VDR BsmI rs1544410 (A > G) variant and Insulin resistance related diseases susceptibility were included." (PMID 28822353, 2017). "The vitamin D has important biological functions, such as modulating immunity system, influencing insulin secretion and improving insulin resistance, which are involved in the etiology of DN and more likely to be influenced by VDR gene polymorphisms." (PMID 28851298, 2017). "Association between VDR BsmI and risk of insulin resistance in Malaysian adolescents presented as OR (unadjusted and adjusted) with 95% CI." (PMID 28617856, 2017).
Insulin resistance (continued). "Adipocyte-specific VDR knockout mice following a high-fat diet for 12 weeks mirrored the vitamin D-deficient humans, displaying increased adipose tissue fibrosis and inflammation and hepatic insulin resistance." (PMID 38892495, 2024). "This study presented the effect of VDR BsmI polymorphism on insulin resistance in children and adolescents and showed that adolescents carrying the BB genotype of VDR BsmI were associated with increased risk of insulin resistance compared to the bb/Bb genotypes." (PMID 38233797, 2024). "So that this study aimed to examine the association of the vitamin D receptor BsmI rs1544410 polymorphism with insulin resistance in Iranian children and adolescent to predict and screen for possible association with type 2 diabetes and target these individuals for appropriate treatment." (PMID 38233797, 2024). "In relation to the pleiotropic effects of vitamin D, correlations have been demonstrated to exist between VDR polymorphisms and various diseases such as insulin resistance, type 2 diabetes, abdominal obesity and responses to calcium and vitamin D supplementation." (PMID 37373338, 2023). "Thus, our observations allowed us to determine the genotype of VDR polymorphisms associated with increased risk of atherosclerosis and insulin resistance." (PMID 37375641, 2023). "Additionally, vitamin D receptor (VDR) polymorphisms are associated with insulin resistance and abnormal glucose metabolism, particularly in some ethnic groups." (PMID 36313112, 2022). "The polymorphisms of VDR may be associated with insulin resistance, which may lead to the risk of gestational diabetes mellitus (GDM)." (PMID 36071390, 2022). "Also researchers found that VDR regulates vitamin D levels and calcium metabolism in the body and these are known to be associated with endocrine dysfunctions, insulin resistance." (PMID 28822353, 2017). "There are other well studied VDR gene polymorphisms such as rs731236 (TaqI), rs7975232 (ApaI) and rs10735810 (FokI) which may influence vitamin D levels, adiposity and insulin resistance in this population." (PMID 28617856, 2017). "Our study was conducted to elucidate whether VDR Gene polymorphisms could predict insulin resistance on a large scale." (PMID 28822353, 2017). "Studies have also discussed VDR gene polymorphisms for associations with the components of MS, which suggest that two major VDR gene polymorphisms (BsmI and FokI) seemed to influence BMI, insulin resistance, and serum HDL cholesterol." (PMID 25106919, 2014). "Using two common VDR polymorphism data suggests they may influence insulin secretion, insulin resistance an serum HDL-cholesterol in our highly heterogeneous population." (PMID 23855914, 2013). "The FokI VDR polymorphism was also associated with indices of insulin resistance among Polish men and among Caucasian Americans, although the studies contradicted each other regarding the specific genotype associated with insulin resistance (FF versus ff)." (PMID 20011094, 2010). "Thus, future clinical study incorporating the VDR polymorphisms and vitamin D intervention may be desirable in our population of young adolescents with insulin resistance." (PMID 28617856, 2017). "However, higher maternal schooling, serum vitamin E, total cholesterol and serum folate concentrations contributed positively with 25-hydroxyvitamin D. In addition, the VDR BsmI was significantly associated with insulin resistance and fasting glucose concentrations." (PMID 26047339, 2015). "Moreover, polymorphisms in vitamin DBP, VDR, and 1, α-hydroxylase genes might link vitamin D deficiency to insulin resistance." (PMID 26120828, 2015). "Despite this our data suggests that VDR polymorphisms may contribute to MetSyn component severity such as insulin secretion, insulin resistance and HDL-cholesterol, findings that warrant further examination in larger cohorts with data permitting genome wide association studies to be made." (PMID 23855914, 2013).
Insulin resistance (continued). "While VDR agonists have demonstrated potential in ameliorating insulin resistance and reducing hepatic lipid accumulation, there remains a need for precise regulation of their metabolic effects and the associated risk of bile acid imbalance." (PMID 40807240, 2025). "A study conducted on knockout VDR mice showed impairment in insulin resistance, and supplementation with vitamin D did improve insulin secretion by stimulating the pancreatic beta cells." (PMID 40004770, 2025). "Although VDR deletion promoted insulin resistance in mouse liver, VDR activation reduced hepatic inflammation and insulin resistance in diet-induced obese mice." (PMID 39339785, 2024). "In this study, we found consistent associations between the VDR-BsmI polymorphism and HOMA-IR, insulin-to-glucose ratio and FIRI insulin resistance index." (PMID 38233797, 2024). "Deletion of VDR in apoE−/− mice fed a high-fat diet showed a protective effect on fatty liver, dyslipidemia, and insulin resistance." (PMID 37175993, 2023). "This association between decreased vitamin D levels and insulin resistance modulates the immune response, induction of systemic inflammation, and induction of insulin resistance through VDR in the muscles and liver." (PMID 36833019, 2023). "Rodent models have shown that it can reduce hepatic inflammation, oxidative stress, and insulin resistance, while in humans hepatic VDR expression is inversely correlated with the severity of steatosis and inflammation." (PMID 37373054, 2023). "Liver-specific deletion of VDR significantly exacerbated hepatic steatosis and insulin resistance and abrogated the protective effect of vitamin D on NAFLD." (PMID 37175993, 2023). "Some evidence from VDR macrophage knockout mice supports the beneficial role of vitamin D by showing that deletion of VDR promotes insulin resistance in liver." (PMID 37111216, 2023). "A recent study showed that activation of VDR acts on resident liver macrophages to reduce liver inflammation and insulin resistance in diet-induced obese mice." (PMID 37111216, 2023). "Anti-inflammatory inhibition of NF-κB signaling by VDR activation improves insulin resistance in obese mice." (PMID 36685522, 2022). "VDRs are also involved in the pathogenesis of insulin resistance; a recent report showed that decreased glucose uptake reduced VDR expression in a diabetic mouse model." (PMID 35147511, 2022). "A recent finding showed that VDR-knockout mice showed insulin resistance with an increased FOXO1 expression in skeletal muscle." (PMID 34371843, 2021). "Studies found that supplementation of Vitamin D can improve hepatic steatosis and insulin resistance by up-regulating vitamin D receptor and overexpression of hepatocyte nuclear factor 4 α." (PMID 34006273, 2021). "The authors reported a protection of high fat diet-fed apoE−/− mice against fatty liver, dyslipidemia and insulin resistance due to deletion of the VDR." (PMID 34827697, 2021). "Few studies have evaluated VDR polymorphisms and/or polymorphisms related to vitamin D metabolism in women with PCOS in relation to insulin resistance, vitamin D status, and metabolic disturbances." (PMID 34684492, 2021). "The main potential mechanism of progression of T2DM was β cell dysfunction due to inflammatory stress and insulin resistance, while VDR was the key regulator of inflammation and beta cell survival." (PMID 32246038, 2020). "Vitamin D affects adipogenesis by regulating the expression of adipocyte transcription factors, such as PPARγ, C/EBPα, and LPL, and through affecting insulin resistance, VDR and unliganded VDR, and adipokine secretion." (PMID 32149047, 2020). "Recent research found that the deletion of macrophage VDR promoted insulin resistance and monocyte cholesterol transport, which accelerated atherosclerosis in mice." (PMID 30119682, 2018).
Insulin resistance (continued). "Extensive cell culture experiments using a dexamethasone as well as a TNF-induced model of insulin resistance were able to show that both agents induced VDR expression." (PMID 30558244, 2018). "Several mechanisms like activation of vitamin D receptor and calcium homeostasis involving impaired pancreatic-β cell function and insulin resistance in T2DM have been suggested." (PMID 25887335, 2015). "Particularly, vitamin D binding to the vitamin D receptor (VDR) influences gut microbial composition, with findings showing increased Bifidobacterium and Akkermansia species, which exert anti-inflammatory effects and improve insulin resistance." (PMID 38257161, 2024). "The 1,25-dihydroxy vitamin D/vitamin D receptor (VDR) axis can influence MAFLD progression by modulating a variety of pathways such as hepatic insulin resistance, oxidative stress, inflammation, and fibrosis, as well as regulating various hepatic cells such as hepatocytes, HSCs, and macrophages." (PMID 38668346, 2024). "Also, the results demonstrated consistent associations between the VDR-BsmI polymorphism and HOMA-IR, insulin-to-glucose ratio and FIRI insulin resistance index." (PMID 38233797, 2024). "It was recently discovered that the deletion of macrophage VDR promotes insulin resistance." (PMID 37895163, 2023). "Vitamin D receptors (VDR) are found on pancreatic islet β cells and act to increase insulin secretion, and several studies indicate that vitamin D supplementation reduced insulin resistance (IR)." (PMID 35365764, 2022). "Moreover, the liver-specific deletion of VDR reduced the rescue effect of vitamin D on hepatic steatosis and insulin resistance in mice, demonstrating that the regulatory role of vitamin D depends mainly on VDR activation." (PMID 35955597, 2022). "A role of Vitamin D3 in metabolism has been derived from genetically engineered mice deficient of Vitamin D receptor, in which the lack of cognate signaling led to proinflammatory alterations linked to development of insulin resistance." (PMID 28474500, 2017). "Recent evidence indicates that genetic variation in the vitamin D receptor may affect PCOS development as well as insulin resistance in women with PCOS." (PMID 29202122, 2017). "The expression of the VDR gene may be responsible for TQ's effect on treating insulin resistance." (PMID 39906623, 2025). "It seems that recruiting healthy children and adolescents in this study may be the main reason for significant association of HOMA-IR and non-significant association of other insulin resistance indices with VDR polymorphism." (PMID 38233797, 2024). "In a study on skeletal muscle-specific VDR-null mice, the mice were found to develop insulin resistance and glucose intolerance with elevated FoxO1 expression and activity, which might be responsible for insulin resistance and impaired glucose metabolism in the skeletal muscle." (PMID 35859985, 2022). "It has been hypothesized that vitamin D3 deficiency has a role in type 1 and type 2 diabetes pathogenesis; in particular, different studies highlighted the leading role of vitamin D receptor (VDR) in maintenance normoglycemia, and the alteration of VDR function has been linked to insulin resistance." (PMID 36091806, 2022). "VDR gene FokI SNPs might contribute to insulin resistance of developing GDM." (PMID 31096931, 2019). "VDR FokI SNPs might contribute to insulin resistance in the development of GDM." (PMID 31096931, 2019). "Interestingly, macrophage VDR deletion increased insulin resistance, indicating that different VDR-related immune functions may overlap with other metabolic roles." (PMID 29659559, 2018). "Recent research found that deletion of macrophage VDR promotes insulin resistance and monocyte cholesterol transport to accelerate atherosclerosis in mice which suggested that VDR dysfunction might result in insulin resistance." (PMID 28822353, 2017).